ILK (integrin linked kinase)
Diseases named in the same sentence as ILK in open-access papers (continued):
Sharing a sentence is not in itself a finding about the gene and the disease.
retinoblastoma (5 papers, 2011 to 2023). A malignant tumor that originates in the nuclear layer of the retina. "These retinal cancer cells, caused by the loss of function of two gene alleles (Rb1) that encode the retinoblastoma tumour suppressor, have elevated expression of ILK." (PMID 24911651, 2014). "ILK is upregulated in human retinoblastomas (Rb), a retinal tumour caused by the loss of function of two gene alleles (Rb1) that encode the first cloned tumour suppressor." (PMID 24911651, 2014). "In contrast to earlier reports, in Rb deficient retinoblastoma cell lines, ILK inhibition decreased cell death following the initiation of multipolar division, increasing the accumulation of multinucleated cells over time." (PMID 24911651, 2014). "Examination of mitotic spindle poles in control and ILK siRNA-treated cells revealed a depletion of ILK at mitotic spindle poles in retinoblastoma and Hela cells." (PMID 37508338, 2023). "In another study, anti-ILK therapy using small molecule inhibitor QLT0267 induces cellular senescence of retinoblastoma cells in an Rb-dependent manner." (PMID 35778385, 2022). "In contrast, data from our lab indicate that ILK inhibition markedly increased the percentage of multinucleated retinoblastoma cells, an effect that correlates with altered mitotic spindle organization and failed cytokinesis." (PMID 24911651, 2014). "Co-staining cells with a polyclonal anti-ILK antibody and an anti-α-tubulin antibody that stains the mitotic spindle indicate that ILK localizes to the centrosomes in retinoblastoma cells." (PMID 24911651, 2014). "In this study, we examine the effects of downregulating ILK on mitotic function in human retinoblastoma cell lines." (PMID 24911651, 2014). "In contrast, we show that ILK inhibition in retinoblastoma cells, markedly increases the percentage of multinucleated cells, an effect that correlates with altered mitotic spindle organization and failed cytokinesis." (PMID 24911651, 2014). "Alternatively, anti-ILK therapies may have different outcomes in cancerous cell lines that depend on retinoblastoma gene expression." (PMID 35778385, 2022). "It is noteworthy that multipolar cytokinesis leading to death did not occur in retinoblastoma cells treated with the ILK inhibitor while 16% of cells undergoing multipolar cell division in DMSO treated cultures died (see Category 4a)." (PMID 24911651, 2014). "Nevertheless, research conducting on lymphoma, renal carcinoma and retinoblastoma revealed a decrease or no ILK expression in tumor tissues." (PMID 21347395, 2011).
acute kidney injury (4 papers, 2010 to 2025). Sudden and sustained deterioration of the kidney function characterized by decreased glomerular filtration rate, increased serum creatinine or oliguria. "This pathway is essential for podocyte function, since mice with podocyte-specific knockout of integrin-linked kinase die from renal failure at the age of 16 weeks." (PMID 21118483, 2010). "Cluster 5 (purple) includes 25 keywords centered on mesenchymal cells, renal fibrosis, microRNA, proliferation, biomarkers, acute kidney injury, cancer, high glucose, ILK, NF-κB, TGF-β, and upregulation." (PMID 40862124, 2025). "Accumulating evidence on kidney diseases suggests that ILK ablation in vivo diminishes the expression of the EMT marker α-smooth muscle actin (α-SMA) and the inducer TGF-β1 in renal tubular epithelial cells in a model of cisplatin-induced acute kidney injury." (PMID 36964489, 2023).
acute myeloid leukemia (4 papers, 2019 to 2025). Acute myeloid leukemia (AML) is a group of neoplasms arising from precursor cells committed to the myeloid cell-line differentiation. "Integrin-linked kinase (ILK) has been implicated in acute myeloid leukemia cells as a key player upstream of AKT in the PI3K prosurvival pathway induced by bone marrow-derived stromal cells." (PMID 30669372, 2019). "Besides being upregulated in several human epithelial cancer types, ILK has been reported as a survival factor in human acute myelogenous leukemia, and as an important factor for T-cell trafficking and survival." (PMID 33504055, 2021). "Blockade of PI3K or ILK signaling with pharmacologic inhibitors LY294002 or QLT0267 resulted in the induction of apoptosis in both leukemic cell lines and in primary acute myeloid leukemia samples." (PMID 30669372, 2019). "Similarly, ILK controls several signaling pathways that are often aberrantly regulated in acute myeloid leukemia (AML), arguing for a potential role for ILK in AML progression." (PMID 35804980, 2022).
Arrhythmia (4 papers, 2016 to 2021). Any cardiac rhythm other than the normal sinus rhythm. "ILK deletion in cardiomyocytes produced a lethal arrhythmogenic cardiomyopathy, suggesting that ILK can participate in development of arrhythmias." (PMID 32144627, 2021). "The functional role of identified ILK interactions in cardiomyocyte function and arrhythmia were subsequently confirmed in human iPSC-cardiomyocytes." (PMID 27408918, 2016). "Contrastly, ILK inhibitor Cpd22 could increase the arrhythmia score after reperfusion (5.0 ± 1.2 vs 3.5 ± 1.5, P < 0.05); moreover, Cpd22 could abolish the effect of LPDT on arrhythmia score (3.6 ± 1.7 vs 1.7 ± 1.3, P < 0.05)." (PMID 32144627, 2021). "Compared with the I/R group, ILK agonist LPDT could significantly reduce the arrhythmia score (1.7 ± 1.3 vs 3.5 ± 1.5, P < 0.05)." (PMID 32144627, 2021).
chronic myeloid leukemia (4 papers, 2012 to 2023). "The quiescent aspect has been investigated in chronic myeloid leukemia (CML) where the integrin-linked kinase (ILK) was pointed out as a survivor mediator critical to tyrosine kinase inhibitors and quiescent stem cells." (PMID 35158868, 2022). "Additionally, an emerging role for ILK-mediated signalling is especially promising in chronic myeloid leukemia (CML), a disease caused by the constitutively active tyrosine kinase BCR-ABL." (PMID 37508338, 2023). "In chronic myeloid leukemia (CML) therapy with tyrosine kinase inhibitors (TKIs), genetic and pharmacological inhibition of ILK has been found to sensitize resistant leukemic stem cells (LSCs)." (PMID 35089438, 2022).
cyst (4 papers, 2022). A sac-like closed membranous structure that may be empty or contain fluid or amorphous material. "Initially, we identified that loss of Parvin or ILK resulted in defective germline cyst encapsulation." (PMID 36531940, 2022). "Periostin binds to αVβ3 and αVβ integrins, activates the integrin-linked kinase (ILK), a component of focal adhesion plaques, and promotes in vitro cyst growth." (PMID 36120538, 2022). "Homozygous deletion of ILK (integrin-linked kinase) gene, whose product is a scaffold protein associated with multiple cellular functions including cell proliferation, resulted in increased caspase-3-mediated apoptosis and reduced cyst size of Pkd1fl/fl;Pkhd1-Cre mice." (PMID 35847973, 2022). "We demonstrate that Parvin and ILK are necessary for germline cyst encapsulation, egg chamber separation, oocyte positioning and assembly of the interfollicular stalk." (PMID 36531940, 2022). "Additionally, periostin/αv/ILK (integrin-linked kinase) and periostin/αvβ3/AKT/mTOR signaling pathways both aggravated the growth of cyst epithelial cells in autosomal dominant polycystic kidney disease (ADPKD)." (PMID 36611844, 2022).
infarction (4 papers, 2011 to 2024). A localised pathological necrosis of tissue resulting from obstruction of the blood supply usually by a thrombus, an embolus, or vascular torsion. "When ILK expression returns to normal, this cardiac adaptive response for infarction is weaken." (PMID 21949693, 2011). "In present study, we observed that ILK expression was temporarily increased in non-ischemic myocardium by infarction, and decreased from 4 to 8 weeks post MI." (PMID 21949693, 2011). "Until 4 weeks after infarction, ILK expression was increased in non-ischemic tissue in parallel with myocytes hypertrophy and compensatory cardiac function." (PMID 21949693, 2011).
lymph node metastasis (4 papers, 2005 to 2022). "ILK expression was significantly associated with tumor grade, T status, lymph node metastasis and stage." (PMID 15631637, 2005). "Further, WISP-1/CCN4 promotes VEGF-C dependent lymphangiogenesis by inhibiting miR-300 (3′-UTR binding repressor of VEGF-C) in vitro via the integrin αvβ3/integrin-linked kinase (ILK)/Akt signalling pathway, and it has been suggested as a potential biomarker for predicting lymph node metastasis." (PMID 34205668, 2021). "However, the expression of ILK protein was significantly associated with tumor grade, T status, lymph node metastasis and stage (p = 0.0169 for tumor grade; p = 0.0006 for T status; p = 0.0002 for lymph node metastasis; p < 0.0001 for stage)." (PMID 15631637, 2005). "It has been shown in pathological results that high ILK expression levels are associated with CRC stage, lymph node metastasis, and patient survival." (PMID 35481240, 2022). "ILK expression was correlated with tumor size, grade, stage, and lymph node metastasis." (PMID 35379935, 2022). "The status of ILK expression might be dependent on the status of lymph node metastasis or other variables." (PMID 15631637, 2005).
Myocardial fibrosis (4 papers, 2012 to 2025). "Meanwhile, a reduction in SMOC2 levels has the potential to mitigate myocardial fibrosis through the suppression of the ILK/p38 signaling pathway." (PMID 40297163, 2025). "Our study implied that the therapeutic silencing of SMOC2 can improve ISO-induced myocardial fibrosis and heart function reduction in vivo, and ameliorate proliferation and collagen deposition of CFs induced by TGFβ in vitro, and the down-regulation of ILK/p38 may be the underlying mechanism." (PMID 36935650, 2022). "We observed that doxorubicin induced myocardial fibrosis and inflammatory cell infiltration, and that ILK treatment prevented both of these processes." (PMID 22348065, 2012). "Moreover, SMOC2 suppression has been shown to alleviate myocardial fibrosis via the ILK/p38 pathway." (PMID 40913254, 2025). "In myocardial fibrosis, SMOC2 participates in regulating the proliferation and differentiation of cardiac fibroblasts through activation of the ILK/p38 signalling pathway." (PMID 40913254, 2025).
nephropathies (4 papers, 2012 to 2025). "Integrin-linked kinase (ILK) is a protein involved in the pathogenesis of many nephropathies with proteinuria." (PMID 35743361, 2022). "Elevated TGF-β1 production might induce the expression of integrin-linked kinase (ILK), a protein that is related to the pathogenesis of many nephropathies that course with proteinuria." (PMID 22844593, 2012). "In this study, we demonstrate that ILK overexpression contributes to mitochondrial dysfunction and increased autophagy in an FA-induced model of kidney damage." (PMID 40076489, 2025). "The increased production of TGF-β might induce the expression of the integrin-linked kinase (ILK), a protein which is related to the pathogenesis of many nephropathies associated with proteinuria." (PMID 24719498, 2014).
oral squamous cell carcinoma (4 papers, 2019 to 2023). "MiR-542-3p, nevertheless, causes growth arrest while inhibits tumor angiogenesis by targeting angiopoietin-2 ILK is also a target gene of miR-542-3p, and previous studies had proved that ILK overexpression is related to the survival and recurrence of oral squamous cell carcinoma patients." (PMID 30636169, 2019).
ovarian tumor (4 papers, 2008 to 2021). "Previous studies have shown that ILK expression is enhanced in advanced ovarian tumors compared to benign ovarian tumors and normal ovarian epithelium." (PMID 26959113, 2016). "ILK expression is also known to be high in advanced ovarian tumors." (PMID 35317111, 2021). "The expression of ILK also has been increased with ovarian tumor grade." (PMID 35317111, 2021). "Our data confirm positive immunoreactivity for ILK in a subset of human ovarian tumor tissues." (PMID 26959113, 2016). "It was also found that β-arrestin acts as an ETAR signal transducer by inactivating GSK-3β through the PI3K/ILK/AKT pathway, thereby promoting WNT signaling and contributing to the chemoresistance, invasion, and metastasis of ovarian tumors." (PMID 28439256, 2017). "Because endothelial cells generally enhance ovarian cancer cell survival, previous attempts to target ovarian tumors included the use of an ETR agonist (Atrasentan, ABT-627) to inhibit cell proliferation and VEGF production and to reduce ILK expression and phosphorylation of GSK-3β." (PMID 28439256, 2017). "A similar trend of heightened expression of both ILK and PDK1 in high-grade ovarian tumours may suggest enhanced activation of upstream PI-3 kinase and/or PPARβ cascades required for tumour progression." (PMID 18349831, 2008).
pulmonary fibrosis (4 papers, 2021 to 2023). Chronic progressive interstitial lung disorder characterized by the replacement of the lung tissue by connective tissue, leading to progressive dyspnea, respiratory failure, or right heart failure. "The other upregulated pathways included “regulation of the EMT in development pathway”, “actin cytoskeleton signaling”, “pulmonary fibrosis idiopathic signaling pathway”, and “integrin linked kinase (ILK) signaling”." (PMID 36900319, 2023). "In our study, the most relevant pathways that predicted by the Ingenuity pathway analysis, Pulmonary fibrosis, Transforming growth factor signalling and Hippo pathway, were all of them related to EndMT and ILK pathways." (PMID 37452166, 2023). "Studies in bleomycin-induced pulmonary fibrosis in animal models showed decreased ILK expression during early stages of fibrosis." (PMID 34960806, 2021).
renal carcinoma (4 papers, 2011 to 2025). A carcinoma arising from the epithelium of the renal parenchyma or the renal pelvis. "In renal carcinoma cells (RCCs), oleic acid, an FFA, enhanced Akt phosphorylation via the GPR40/integrin‐linked kinase (ILK) axis." (PMID 40229990, 2025). "High-level expression of POSTN can promote EMT via ILK/AKT/mTOR pathway in renal carcinoma." (PMID 35508298, 2022).
aortic aneurysm (3 papers, 2013 to 2022). A ruptured aneurysm located in the wall of the proximal portion of the descending aorta proceeding from the arch of the aorta. "Taken together, this suggests that disruption of ILK-Pinch1 signaling in NCCs results in reduced Smad3 phosphorylation that ultimately causes the aortic aneurysms phenotype." (PMID 23744273, 2013). "Moreover, the data suggest that disruption of ILK signaling in NCCs leads to aortic aneurysms through a signaling pathway that involves reduced Smad3 signaling." (PMID 23744273, 2013). "The phenotypic similarities among these mutant mice suggest that the β1 integrin signaling pathway involving ILK, Pinch1 and Rac1 is crucial for vascular function and might be altered in human disorders that are characterized by aortic aneurysms." (PMID 23744273, 2013). "The role of ILK in NCC morphogenesis and potentially in aortic aneurysm development has not yet been investigated." (PMID 23744273, 2013).
chronic lymphocytic leukemia (3 papers, 2016 to 2019). "T315 has previously been identified as an integrin-linked kinase inhibitor and potential therapeutic against chronic lymphocytic leukemia." (PMID 30515144, 2018).
endometriosis (3 papers, 2016 to 2024). The growth of functional endometrial tissue in anatomic sites outside the uterine body. "More importantly, disturbances in intracellular signaling pathways related to the pathological expression of EMT mesenchymal biomarkers (TGF-β1, SMAD3 and ILK) may have clinical significance in the diagnostic and therapeutic aspects of endometriosis." (PMID 36768775, 2023). "In our study, an increase in the level of ILK expression in the endometrium (EUE) of women with endometriosis compared to the control group indicates the importance of ILK in the pathogenesis of endometriosis." (PMID 36768775, 2023). "An interesting result of our work is an increase in ILK expression along with an increase in pain severity in women with endometriosis." (PMID 36768775, 2023). "Consistent with this, our previous study demonstrated that periostin enhanced the adhesion, migration, and invasion of ESCs through ILK-Akt pathway in endometriosis." (PMID 27034956, 2016). "Additionally, the purpose of the study was to analyze the correlation between TGF-β1, SMAD3, ILK and miR-21 expression levels and the clinical features and biochemical parameters of patients with endometriosis." (PMID 36768775, 2023). "The additional Mann–Whitney U test also showed statistically significantly lower expression of TGF-ß1, SMAD3 and ILK in ectopic lesions compared to matched eutopic endometrium in women with endometriosis (p = 0.023471, p = 0.026057 and p = 0.006639; respectively)." (PMID 36768775, 2023). "Therefore, inhibition of the expression and activity of ILK is being increasingly considered as a new target in the prevention of endometriosis and a possible therapeutic alternative to hormone therapy, often effective but carrying numerous side effects." (PMID 36768775, 2023). "Interestingly, in our study, the ILK gene expression profiles in eutopic and ectopic tissue in endometriosis patients differed, manifesting the upregulation of ILK in the eutopic endometrium and downregulation in endometrial lesions compared to normal endometrium." (PMID 36768775, 2023). "As the initial stage of endometriosis is considered to be the adhesion ability of the exfoliated endometrial tissues retreating into the pelvic cavity, research also focuses on the specific adhesive particles, such as ILK, regulating the ability of endometrial stromal cells to adhere." (PMID 36768775, 2023). "Therefore, in the future, we plan to analyze cell lines regarding the effect of miR-21, TGF-β1, SMAD3, and ILK expression levels on the biological functions of endometrial cells, which will provide innovative theoretical references in terms of molecular targets for endometriosis treatments." (PMID 36768775, 2023). "TGF-ß1 is known to affect the expression of growth factor (NGF) and neurotrophin-3 (NT-3) mRNA, and as ILK remains under TGF-ß1 control, the involvement of ILK in the mechanism of pelvic pain in women with endometriosis is therefore possible." (PMID 36768775, 2023). "Endometriosis patients manifested higher TGF-β1, SMAD3, and ILK expression levels in the eutopic endometrium and a decreased expression level in the ectopic lesions in relation to control tissue." (PMID 36768775, 2023). "Moreover, the evidence of published studies indicates that ILK increases the ability of cells to migrate and invade through EMT induction, which plays a significant part in the initial formation of endometriosis." (PMID 36768775, 2023). "The expression levels of the TGF-ß1, SMAD3, ILK and miR-21 genes were assessed in PBMCs obtained from patients with endometriosis and in PBMCs from patients without endometriosis, who constituted the control group (C2)." (PMID 36768775, 2023). "The eutopic endometrium of women with endometriosis showed higher expression of the mRNA TGF-β1, SMAD3 and ILK, and the level of miR-21 did not change compared to the endometrium of healthy participants." (PMID 36768775, 2023).
endometriosis (continued). "For ILK, the RQ value was 0.357348 in the ECE and 7.755932 in the EUE of patients with endometriosis, while in the endometrium of women without endometriosis (C1), the mean RQ value was 2.524812." (PMID 36768775, 2023). "To the best of our knowledge, we were the first to assess changes in the level of expression of TGF-β1, SMAD3, ILK and miR-21 in the PBMC of patients with and without endometriosis." (PMID 36768775, 2023).